BIRC5 (baculoviral IAP repeat containing 5)
Diseases named in the same sentence as BIRC5 in open-access papers (continued):
Sharing a sentence is not in itself a finding about the gene and the disease.
hyperprolactinemia (1 paper, 2013). Abnormally high level of prolactin in the blood. "An increased expression of BIRC5 in immature B cells was found only in the SLE mice in response to hyperprolactinemia." (PMID 24454471, 2013).
inflammatory bowel disease (1 paper, 2025). A spectrum of small and large bowel inflammatory diseases of unknown etiology. "Topological analysis identified 14 core targets based on centrality metrics, and five key intersection genes (CASP7, BIRC5, CDK9, STAT1, RELA) were highlighted as significantly associated with core network functions, including inflammatory bowel disease and apoptosis." (PMID 41515060, 2025).
influenza (1 paper, 2021). An acute viral infection of the respiratory tract, occurring in isolated cases, in epidemics, or in pandemics; it is caused by serologically different strains of viruses (influenzaviruses) designated A, B, and C, has a 3-day incubation period, and usually lasts for 3 to 10 days. "Cluster IV contained several immunoglobulin genes, in addition to MKI67 (Ki67), TOP2A and BIRC5 (Survivin), which are associated with proliferation, likely representing a plasmablast signature as has been reported at Day 7 after immunization with the influenza vaccine." (PMID 33720973, 2021).
invasive carcinoma (1 paper, 2021). A carcinoma that is not confined to the epithelium, and has spread to the surrounding stroma. "However, S100A8, LAG3, CXCL10, CXCL9 and BIRC5 showed a difference in fold change between DCIS and invasive carcinoma although statistically not significant (adjusted p value > 0.05)." (PMID 34504204, 2021).
ischemic stroke (1 paper, 2022). A stroke disorder caused by obstruction of blood flow to the brain, due to thrombotic (local blood clot formation) or embolic (due to a blood clot or other material traveling from another site) event. "The correlation between the SNP of BIRC5 rs2071214 and susceptibility to ischemic stroke was reported previously." (PMID 35685607, 2022). "Herein, the potential association of the allelic variation of BIRC5 rs2071214 with the collateral circulation and severity of patients with ischemic stroke was explored deeply to examine the possible mechanism." (PMID 35685607, 2022).
large cell lymphomas (1 paper, 2023). "Clusters 3.4 and 3.6 also featured upregulation of genes implicated in large cell lymphomas, and notably overlapping with several genes enriched in RT tumors compared to matched CLL precursors, including Birc5, Cdk1, Mki67, and Npm1." (PMID 36609611, 2023).
laryngeal carcinoma (1 paper, 2022). Carcinoma that arises from the laryngeal epithelium. "Our findings revealed that BIRC5 could promote laryngeal cancer tumorigenesis and contribute to the poor prognosis of LSCC patients." (PMID 35178302, 2022).
leukoplakia (1 paper, 2018). A white patch or plaque on a mucous membrane that cannot be characterized clinically or pathologically as any other disease. "Although a direct comparison between these two databases (GSE10121 and GSE85195) was not possible, our comparative analysis indicated that the BIRC5 mRNA was upregulated in OSCC compared both to leukoplakia and oral normal tissue." (PMID 30205554, 2018). "Results of the comparative analysis between OSCC samples and non-cancer tissues revealed that the mRNA expression of BIRC5 was higher in the cancer samples compared both to leukoplakia samples and to normal tissue in healthy (non-cancerous) patients." (PMID 30205554, 2018).
liver failure (1 paper, 2023). A liver disease characterized by the liver losing or has lost all of its function. "The genes identified in this study, especially Birc5, may be used to evaluate the liver state of patients with liver failure." (PMID 37315292, 2023).
low grade glioma (1 paper, 2022). A grade I or grade II glioma arising from the central nervous system. "However, no studies have yet focused on the immunological function and mechanisms of upstream BIRC5 regulation in the progression of low-grade gliomas (LGG)." (PMID 35309512, 2022).
lung fibrosis (1 paper, 2022). "Notably, both FOXM1 and BIRC5 were found elevated in IPF-derived lung fibroblasts, and conditional deletion of Foxm1 in mouse fibroblasts accelerated lung fibrosis resolution following bleomycin challenge." (PMID 35167499, 2022).
male breast carcinoma (1 paper, 2012). A malignant neoplasm involving the male breast. "Among the other genes studied, copy number gain of MED1, PRDM14, and BIRC5 were associated with a high grade phenotype, indicating that these genes play a role in the development or progression of aggressive male breast cancer." (PMID 22527098, 2012). "Also MED1, PRDM14, MTDH, and BIRC5 seem to be important in the development or progression of high grade male breast cancer." (PMID 22527098, 2012).
mastitis (1 paper, 2013). Inflammation of breast tissue during lactation or postpartum due to an obstructed duct or infection. "Interestingly, BIRC5 and SOCS3 are located in the region of QTL markers associated with somatic cell score (SCS) in NRF, and elevated SCS is often an indicator of subclinical mastitis in cattle infected with S. aureus." (PMID 24341851, 2013).
mental retardation syndrome X-linked (1 paper, 2022). "AT-rich interactive domain 1A (ARID1A), aurora kinase B (Aurora-B), α-thalassemia/mental retardation syndrome X-linked (ATRX), and baculoviral IAP repeat-containing 5 (BIRC5) are also among the genes involved in cancer drug resistance." (PMID 35715750, 2022).
myelofibrosis (1 paper, 2024). A partial or complete replacement of the bone marrow stroma by fibrous tissue. "In the present study, BIRC5 expression was significantly increased in primary myelofibrosis patients compared to healthy donors." (PMID 39261151, 2024).
myeloid leukemia (1 paper, 2008). A clonal proliferation of myeloid cells and their precursors in the bone marrow, peripheral blood, and spleen. "In particular, a recent report has shown that BIRC5 (survivin), which inhibits apoptosis and controls cell division, was up-regulated in many brain cancers but repressed both in vitro and in vivo, following TopoI inhibition in myeloid leukemia cells." (PMID 18694480, 2008).
neuroendocrine tumors (1 paper, 2022). "A recent in vitro study on human cell lines of neuroendocrine tumors (NETs) showed increased BIRC5 expression in irradiated cells, additionally BIRC5 knockdown resulted in reduced cellular proliferation but not significantly increased radiosensitivity." (PMID 35331169, 2022).
oropharyngeal squamous cell carcinomas (1 paper, 2023). "The aim of this study was to investigate BIRC5 polymorphisms in oral and oropharyngeal squamous cell carcinomas and to correlate them with clinicopathological data." (PMID 38139318, 2023).
pancreatic NET (1 paper, 2020). "We also found genomic data for 8 pancreatic NET in TCGA and a positive correlation was found between BIRC5 mRNA expression and RSI in pancreatic NET as well (R = 0.824, p = 0.012)." (PMID 32577168, 2020).
psoriasis vulgaris (1 paper, 2023). Plaque psoriasis is the most common presentation of psoriasis. "In the GSE6710 dataset, BIRC5, NAMPT, and BCL2 had high diagnostic values in both mild and moderate-severe psoriasis vulgaris samples." (PMID 38129460, 2023). "We identified three autophagy-related genes (BIRC5, NAMPT and BCL2) with high diagnostic value for the early diagnosis of psoriasis vulgaris through bioinformatics analysis and clinical samples." (PMID 38129460, 2023). "The expression levels of BIRC5, NAMPT, and BCL2 were tested by ELISA in the blood samples of patients with psoriasis vulgaris and healthy controls." (PMID 38129460, 2023). "Therefore, we considered three genes (BIRC5, NAMPT, and BCL2) as potential biomarkers for the early diagnosis of psoriasis vulgaris." (PMID 38129460, 2023). "Therefore, we hypothesized that BIRC5, NAMPT, and BCL2 might serve as biomarkers for the early diagnosis of psoriasis vulgaris." (PMID 38129460, 2023). "Therefore, we hypothesized BIRC5, NAMPT, and BCL2 as potential biomarkers for the early diagnosis of psoriasis vulgaris using bioinformatics analysis and clinical samples." (PMID 38129460, 2023). "Therefore, we proposed that BIRC5, NAMPT and BCL2 may be as potential biomarkers for the early diagnosis of psoriasis vulgaris." (PMID 38129460, 2023).
renal carcinoma (1 paper, 2025). A carcinoma arising from the epithelium of the renal parenchyma or the renal pelvis. "To assess the importance of these 11 MMCGs, we employed Gene Dependency Scores (gDS) and found that BIRC5, PLG, and EIF4EBP1 had gDS scores below zero in most renal cancer cell lines." (PMID 40591061, 2025).
renal fibrosis (1 paper, 2023). A final common manifestation of a wide variety of chronic kidney diseases characterized by glomerulosclerosis and tubulointerstitial fibrosis. "Second, it would be better to generate renal tubular and fibroblast specific Birc5 knockout mice to fully demonstrate the function of Birc5 as the downstream signaling of TP53RK in renal fibrosis." (PMID 37382161, 2023). "The data above led us to investigate the therapeutic potential of retarding renal fibrosis by targeting TP53RK/Birc5 axis." (PMID 37382161, 2023). "Especially noteworthy is that targeting the TP53RK/Birc5 axis to retard renal fibrosis is of high translational probability, because the TP53RK inhibitor FA is a clinically commonly used antibiotic and Birc5 selective inhibitor YM‐155 is currently in clinical phase 2 trials." (PMID 37382161, 2023).
retinal degeneration (1 paper, 2022). Degeneration of the retina. "Thus, because the harmful effects of short-wavelength light can include retinal degeneration, it would be interesting to investigate whether changes in Birc5 expression in the retina are associated with exposure to monochromatic light at various wavelengths." (PMID 36059433, 2022).
rotator cuff tear (1 paper, 2018). "Birc5, which is known to play an important role in apoptosis, seemed to play a similar role in the rotator cuff muscle after the rotator cuff tear." (PMID 30671462, 2018).
Splenomegaly (1 paper, 2021). Abnormal increased size of the spleen. "Moreover, the spleen of mice in the Birc5-/- group had no evident splenomegaly." (PMID 34421916, 2021).
squamous intraepithelial lesions (1 paper, 2025). "In recent studies, BIRC5 expression has been shown to correlate with high-risk squamous intraepithelial lesions (HSILs), where its mRNA levels in liquid-based cytology (LBC) samples exhibited 90% sensitivity and moderate specificity (58%)." (PMID 40508156, 2025).
Stroke (1 paper, 2022). Sudden impairment of blood flow to a part of the brain due to occlusion or rupture of an artery to the brain. "The identification of the factors that promote stroke will help prevent and control this disease, while this study provides the clinical evidence that the polymorphism of BIRC5 could potentially serve as a biomarker to evaluate the severity of stroke." (PMID 35685607, 2022). "Moreover, compared with the patients with NIHSS ≥ 6, the patients with a GG genotype had a significantly higher percentage, suggesting that the BIRC5 GG genotype of rs2071214 was negatively correlated with stroke severity." (PMID 35685607, 2022).
T-cell leukemia (1 paper, 2020). A malignant disease of the T-lymphocytes in the bone marrow, thymus, and/or blood. "In adult T-cell leukemia, TCF4 up-regulates BIRC5 expression, which probably increase the viability of cell viability." (PMID 32714094, 2020).
teratozoospermia (1 paper, 2022). "As for men with oligo-astheno-teratozoospermia, it was reported that both concentration and motility of spermatozoa were positively associated with the expression levels of BIRC5 in seminal plasma." (PMID 35833143, 2022).
vascular tumor (1 paper, 2018). "Differential BIRC5 expression was found at different tumor status, pathological stages, histological grades, T stages and vascular tumor cell types." (PMID 29707114, 2018).
cancer (375 papers, 2008 to 2026). A tumor composed of atypical neoplastic, often pleomorphic cells that invade other tissues. "BIRC5 is widely recognized for its positive association with cell survival, drug resistance, and cancer metastasis." (PMID 40471223, 2025). "Overexpression of BIRC5 is frequently observed in various cancers and is linked to tumor initiation and progression, making it a valuable diagnostic and prognostic biomarker as well as a potential therapeutic target." (PMID 41153630, 2025). "Bioinformatics analysis has revealed that BIRC5 is highly expressed in many cancers, promotes tumor progression and is strongly associated with poor prognosis." (PMID 39944135, 2025). "For instance, BIRC5 (survivin) is overexpressed in multiple cancers, including PDAC, and has been proposed as a diagnostic and therapeutic target." (PMID 41209344, 2025). "This mechanistic insight further reinforces BIRC5’s potential as a prognostic marker and therapeutic target, particularly in cancers where its expression is closely linked to poor prognosis and aggressive tumor behavior." (PMID 39703228, 2024). "Baculoviral inhibitor of apoptosis repeat containing 5 (BIRC5) is closely linked with high-grade cancer and differentiation." (PMID 39619695, 2024). "Most of these cancers exhibited four to five distinct molecular subtypes, underscoring the strong association between BIRC5 expression and tumor classification." (PMID 39703228, 2024). "We confirmed the elevated expression of Birc5 (encoding survivin) in cancer relative to the other subsets." (PMID 38413714, 2024). "ROC analysis showed that BIRC5 exhibited strong diagnostic potential, with high AUC values (>0.9) in several cancers." (PMID 39703228, 2024). "The ROC curve analysis demonstrates BIRC5’s robust diagnostic performance, with AUC values exceeding 0.9 in several cancer types, highlighting its potential as a cancer biomarker." (PMID 39703228, 2024). "The analysis revealed a general trend where high BIRC5 expression was associated with a reduced infiltration of these immune cell subtypes in most cancers." (PMID 39703228, 2024). "The BIRC5 gene encodes survivin, which is an antiapoptotic protein and has been extensively studied as a therapeutic cancer target." (PMID 39255035, 2024). "BIRC5 overexpression is associated with mitosis, proliferation, migration, and immune infiltration in different cancers; however, its clinical impacts and associations with the tumor microenvironment (TME) are still not well understood." (PMID 37509650, 2023). "The network showed the BIRC5 gene is the most connected node that is associated with 17 cancers and tumor-related diseases." (PMID 36723760, 2023). "The role of BIRC5 polymorphisms has been studied in various cancers, and several polymorphisms have been associated with susceptibility, survival, and age of onset." (PMID 38139318, 2023). "YY1′s dual role as a transcription factor can be explained by the cellular contexts or mutated binding sites within the BIRC5 promoter of cancer cells, impacting the binding of YY1." (PMID 37686541, 2023). "The therapeutic effect of YM155, a BIRC5 inhibitor, has been shown in several cancers; however, the effect and underlying mechanism in RCC subtypes were not previously understood." (PMID 38203388, 2023). "In total, 14/33 cancer types were found to be associated with more unfavorable OS in patients with tumor samples expressing BIRC5, whereas BIRC5 expression was linked to a protective effect in 2/33 cancer types (LUSC and OV)." (PMID 35331169, 2022). "Our findings suggest that BIRC5 overexpression is associated with the initiation and progression of several cancer types, and thereby a promising prognostic biomarker." (PMID 35331169, 2022). "Together, these findings indicate that BIRC5 expression is closely associated with prognosis in diverse human cancers." (PMID 35309512, 2022).
cancer (continued). "Higher BIRC5 expression was also linked to shorter progressive-free interval (PFI) for 14/33 cancer types (4/14 after adjusting for both age and tumor grade and 10/14 after adjusting only for age)." (PMID 35331169, 2022). "In several different cancer types, we observe an association between higher BIRC5 expression and unfavorable OS." (PMID 35331169, 2022). "For instance, we identified phase shifted transcript pairs from different cancer hallmark genes such as BIRC5 in HCT116_WT, PCGF2 in HCT116_ARNTLKO, ABCA2 in HCT116_NR1D1KO, and CHD8 in HCT116_PER2KO." (PMID 35552415, 2022). "BIRC5 gene expression is associated with more advanced stages of cancer, tumor grades, levels of metastasis, and aggressive subtypes of BC, including TNBC." (PMID 36358602, 2022). "ICGC data showed that eight patients affected by different cancer types harbored eight different BIRC5 mutations." (PMID 35331169, 2022). "For 14/33 cancer types, higher BIRC5 expression was linked to worse overall survival (OS, 4/14 after adjusting for both age and tumor grade and 10/14 after adjusting only for age)." (PMID 35331169, 2022). "COSMIC data revealed 210 unique cancer samples with somatic mutations in the BIRC5 gene, of which 33 were classified as pathogenic mutations." (PMID 35331169, 2022). "BIRC5 is a gene identified in the analysis as a DEG associated with the establishment of cancer in the LC&LD and LC&OC networks, and its presence in the LC-BC and LC-LK CCPs suggests its importance in tumor process." (PMID 36101460, 2022). "Survivin is a member of the IAP family encoded by the BIRC5 gene, and is an apoptosis suppressor expressed primarily in embryonal development, and upregulated in cancer." (PMID 35568716, 2022). "The present manuscript aims at collecting and describing the most recent evidences concerning the role of the two IAPs BIRC3 and BIRC5 focusing on cancer, in order to underline the common characteristics and to shed light on the main controversies." (PMID 33413657, 2021). "BIRC5 is commonly upregulated within tumours and its overexpression is associated with a worse prognosis in a number of different cancer types, likely due to a failure of programmed cell death in the affected cells." (PMID 34638823, 2021). "Overexpression of BIRC4 and BIRC5 genes has been described in many cancers, and high expression of survivin and XIAP was associated with poor prognosis." (PMID 33673050, 2021). "An important role in cancers is played by livina—a protein encoded by the BIRC7 (Baculoviral IAP Repeat Containing 5) gene." (PMID 33673050, 2021). "Survival analysis demonstrated that a higher BIRC5 protein or mRNA level was associated with poor survival in all cohorts and for different cancer subtypes." (PMID 34064473, 2021). "We found that BIRC5 directly engages with genes involved in pathways associated with the hallmarks of cancer including apoptosis and mitosis." (PMID 34638823, 2021). "Recently, serum BIRC5 levels has been found to be positively linked to early diagnosis in majority of human cancers." (PMID 34712656, 2021). "Survivin is a protein encoded by the BIRC5 gene that plays a role in cell division by inhibiting apoptosis and regulating the process of mitosis in embryonic and cancer cells." (PMID 32751449, 2020). "Higher BIRC5 expression was predominantly associated with worse survival across different cancers with one exception in THYM where higher BIRC5 was associated with longer overall survival." (PMID 31964418, 2020). "YM155 was originally developed as an anti-cancer drug that targets Survivin (encoded by BIRC5), which is highly expressed in many cancer cell types, as well as hPSCs." (PMID 31157201, 2019). "Among the genes interacting with hsa-miR-497-5p in this network, BIRC5, a well-known cancer-related gene encoding survivin, has been proven to be upregulated by TGF-β to modulate the cell cycle and apoptosis in various types of cancer." (PMID 31761783, 2019).